HP (haptoglobin)
Diseases named in the same sentence as HP in open-access papers (continued):
Sharing a sentence is not in itself a finding about the gene and the disease.
Obesity (continued). "In analogy with zonulin, haptoglobin levels have been shown to correlate with BMI and to be elevated in obesity." (PMID 28282855, 2017). "Serum levels of interleukin-6, and haptoglobin were found to be strong predictors of complications in severe obesity by linear regression analysis." (PMID 27275205, 2015). "Obesity tended to decrease haptoglobin isoforms of higher MW and increase low MW isoforms, with this last change found to be significant after FDR analysis." (PMID 24949022, 2014). "Our present results indicate that serum haptoglobin concentration, and the number of women presenting with serum levels above the upper limit of the normal range, increase with obesity." (PMID 19440331, 2009). "Haptoglobin is a glycoprotein involved in the acute-phase response to inflammation, and some studies reported higher levels of this protein in the blood of individuals with obesity." (PMID 40565086, 2025). "Haptoglobin-hemoglobin complex play a role in attenuating oxidative damage and tissue protection; serum binding bead levels are elevated in populations with cardiovascular disease, malignancy, inflammation, infection, and obesity." (PMID 40264951, 2025). "Indeed, the mRNA expression levels of Mcp1, Saa3, Haptoglobin, and Il10 exhibited a significant increase with the combined influence of aging and obesity, thus confirming the individual impacts of age and diet across all experimental groups." (PMID 39009694, 2024). "Similarly, our results showed that Haptoglobin was an important up-regulated protein in the saliva of pregnant women with obesity and periodontitis." (PMID 36355174, 2022). "In human studies, haptoglobin is considered as an indicator of obesity." (PMID 35566276, 2022). "In the same study, the authors found the HP rs2000999 G allele to be related to haptoglobin levels, but not obesity." (PMID 32752277, 2020). "One possible mechanism for such increased haptoglobin production in obesity is a TNFα-mediated induction, since mice overexpressing TNFα present higher levels of haptoglobin and obese mice lacking this cytokine in white adipose tissue (WAT) resulted in a downregulation of adipose haptoglobin." (PMID 32752277, 2020). "Increased CRP and haptoglobin levels are indicators of inflammation observed in human obesity." (PMID 30005082, 2018). "Moreover, we propose a number of genes as candidates for fat content inpigs (LIPE, LXRA, HP), which were previously investigated in termsof human obesity." (PMID 29658965, 2018). "Interestingly, linear regression analysis revealed that serum levels of IL-6 and haptoglobin play a significant role in the pathogenesis of obesity." (PMID 27275205, 2015). "Indeed haptoglobin concentrations have been shown to positively increase in proportion to the severity of obesity." (PMID 25096020, 2014). "One such inflammatory condition is obesity, where an increase in the central fat compartment leads to a state of relative hypoxia in the adipocytes and a release of a number of inflammatory markers including haptoglobin." (PMID 25096020, 2014). "However haptoglobin has several other functions that may be relevant to both implantation and obesity." (PMID 25096020, 2014). "Therefore, we conducted the present study hypothesizing that haptoglobin and its polymorphism might mediate the associations of PCOS with hyperferritinemia and increased body iron stores, obesity and disorders of glucose tolerance." (PMID 19440331, 2009). "Haptoglobin and SPLUNC were present at lower levels in participants with obesity, but their levels increased one month after bariatric surgery." (PMID 40565086, 2025). "Serum haptoglobin levels were directly related to BMI, HOMA-IR, fasting insulin and blood glucose levels in a group of obese women, and serve as a marker of obesity." (PMID 32752277, 2020).
Obesity (continued). "Furthermore, hydroxyproline, a possible stress marker but also an obesity marker, was also a discriminant metabolite in our metavariable PlasmaLD2, while our metavariable GenusD1 including Escherichia-Shigella was positively correlated with blood haptoglobin, another inflammatory marker." (PMID 32260190, 2020). "BMI-predictive proteins included established obesity markers and obesity-related proteins, including adiponectin, CRP, IGFBP1, IGFBP2, PRG4, SHBG, apolipoproteins (APOA4, APOF) and inflammatory response proteins (A2M, APCS, LBP, HSPG2, HP, AOC3, ITGB1, VNN1)." (PMID 39972214, 2025). "Even when serum haptoglobin levels increase with insulin resistance and obesity, neither serum haptoglobin levels nor the haptoglobin genotype were related to the development of disorders of glucose tolerance in our series of young premenopausal women." (PMID 19440331, 2009). "However, as for ApoA1, serum haptoglobin variability observed in T2DM, obesity, and COVID-19 could also be directly due to the intestine, such as changes in endothelial permeability." (PMID 35327501, 2022). "Haptoglobin was significantly and positively associated with T2DM in men without obesity." (PMID 35327501, 2022). "Haptoglobin was significantly and positively associated with T2DM in men with or without obesity." (PMID 35327501, 2022). "Furthermore, haptoglobin phenotypes influence serum ferritin concentrations, and increased ferritin concentrations have been described not only in PCOS, but also in insulin resistant disorders such as obesity, type 2 diabetes mellitus and the metabolic syndrome." (PMID 19440331, 2009). "Distribution of haptoglobin genotypes in the presence or absence of PCOS, obesity, or disordered glucose tolerance." (PMID 19440331, 2009).
hemolysis (35 papers, 2010 to 2026). Disruption of the integrity of the erythrocyte membrane causing release of hemoglobin. "Reduced serum haptoglobin level and increased accumulation of hemosiderin in the kidney suggested that intravascular hemolysis causes reduced half-life of erythrocytes." (PMID 33328561, 2020). "Hemopexin, similarly to haptoglobin, is sensitive to intravascular hemolysis, as it binds free heme, which is released after hemoglobin degradation." (PMID 40429487, 2025). "RBC markers, including RBC count, hemoglobin concentration, and haptoglobin levels, were measured to assess hemolysis, which has been reported to occur during prolonged training sessions and endurance events." (PMID 41357163, 2025). "A full-flow microaxial pump (Impella 5.5) seems advantageous regarding systemic inflammatory response syndrome (SIRS) and acute hemolysis, indicated by lower IL-6 and higher haptoglobin levels, compared with smaller Impella devices." (PMID 39768841, 2024). "The importance of protective mechanisms against the adverse effects of intravascular hemolysis in organisms with a blood circulation is highlighted by the evolutionary early appearance and conservation of haptoglobin." (PMID 35193645, 2022). "In our studied population, five patients had increased free hemoglobin and decreased haptoglobin, but normal serum bilirubin levels, considered to indicate pure intravascular hemolysis." (PMID 32126966, 2020). "When intravascular hemolysis occurs, free hemoglobin is released into the plasma and binds rapidly to haptoglobin." (PMID 32011483, 2020). "Systemic TMA occurred in 25% of the patients, being their mean hemoglobin and platelet levels 8.7±1.5g/dL and 95±46 x 103/μL, respectively, and the presence of schistocytes (95%) and reduced haptoglobin (53%) were the most common hemolysis criteria found." (PMID 31923282, 2020). "In HUS, reticulocyte numbers, indirect bilirubin, and LDH levels increase as a result of intravascular hemolysis, and haptoglobin levels decrease." (PMID 27460033, 2016). "An increased haptoglobin level does not rule out TA-TMA as it indicates ongoing systemic inflammation as an acute-phase response along with hemolysis and is associated with poor outcomes in TA-TMA." (PMID 40406401, 2025). "A plasma-derived haptoglobin, available commercially in Japan, has been used to treat severe hemolysis during blood transfusions, extracorporeal circulation, and thermal injury, and limited evidence suggests that haptoglobin administration during cardiopulmonary bypass can reduce postoperative AKI." (PMID 38049866, 2023). "While we measured the parameters of iron metabolism, also determination of the markers of post-exercise hemolysis and its severity, such as bilirubin, haptoglobin, methemalbumin and free hemoglobin, would add considerably to our knowledge of beneficial effects of chokeberry juice in elite athletes." (PMID 25298754, 2014). "Were the observed changes the result of increased intravascular hemolysis, prompted by the increased extracellular hemoglobin (plasma hemoglobin) and serum bilirubin and decreased plasma concentrations of haptoglobin found in this study in men undergoing ten and twenty WBC treatments?" (PMID 24695100, 2014). "The proinfammatory vasculotoxic effects of intravascular hemolysis are modulated by plasma hemoglobin and heme clearance via the haptoglobin/CD163 system and the hemopexin/CD91 system, respectively, and detoxification through the heme oxygenase/ferritin system." (PMID 25506596, 2013). "The importance of protective mechanisms against theadverse effects of intravascular hemolysis in organisms with a blood circulation ishighlighted by the evolutionary early appearance and conservation of haptoglobin.CFH may also originate from direct mechanical injury of red cells in thevasculature." (PMID 38748856, 2024).
hemolysis (continued). "The lack of changes in haptoglobin concentration after the reduced-calorie diet excluded the hypothesis of hemolysis as the cause of hyperbilirubinemia." (PMID 39064690, 2024). "A recent study showed that intravenous infusion of exogenous haptoglobin in rats attenuates hemoglobin-impaired muscle contraction, and it is therefore recommended for improved muscle metabolic control and exercise tolerance in patients suffering from acute or chronic hemolysis." (PMID 36671013, 2023). "Hence, hemolysis frequently occurred in runners who training at high-intensity on a daily basis, and it is possible that subjects in the present study observed chronically low haptoglobin levels." (PMID 35565873, 2022). "In our study, the incidence of hemolysis was significantly higher among patients on ECMO compared to those without ECMO (81% vs. 22%), with significant depletion in the markers haptoglobin and hemopexin throughout the whole study." (PMID 40429487, 2025). "In situations of ongoing chronic hemolysis (e.g. SCD), when the binding capacity of haptoglobin and hemopexin is saturated, free heme and free hemoglobin are delivered to the kidney." (PMID 26406992, 2015). "Laboratory evaluation demonstrated severe intravascular hemolysis with markedly elevated lactate dehydrogenase, indirect hyperbilirubinemia, undetectable haptoglobin, and a negative direct Coombs test." (PMID 41658679, 2026). "Although the present study did not measure haptoglobin to quantify hemolysis, we did not detect any apparent signs of intravascular hemolysis among the included patients." (PMID 30181880, 2018). "The decrease in indices of the erythrocytic system, plasma hemoglobin and bilirubin, with a simultaneous decrease in haptoglobin concentrations after 10 and 20 WBC treatments, may be due to increased intravascular hemolysis." (PMID 24695100, 2014). "Additionally, intravascular hemolysis (IVH) was quantified using several indirect markers (LDH, α-HBDH, haptoglobin and hemopexin), which all showed elevated IVH in SMA." (PMID 20386613, 2010). "Further studies may prospectively validate our findings by the measurement of CFH and determine whether treatments aimed at replenishing haptoglobin levels or at lowering iron levels might be beneficial in ARDS patients undergoing ECMO who are often exposed to chronic and subclinical hemolysis." (PMID 39078479, 2025).
lung cancer (34 papers, 2011 to 2026). A malignant neoplasm involving the lung. "It has been reported that haptoglobin is associated with the occurrence and development of a variety of tumors, including lung cancer 33, pancreatic cancer 34, and liver cancer." (PMID 31413735, 2019). "α 2,6-linked tri-sialylated triantennary glycan of haptoglobin from the serum was a potential glyco-biomarker for the diagnosis of human lung cancer." (PMID 24722010, 2014). "The specific glycoform of α2,6-linked tri-sialylated triantennary glycan of haptoglobin associated with human lung cancer was identified and quantified using MALDI-Q/TOF-MS/MS, MALDI-TOF/TOF and nanoESI-orbitrap mass spectrometers." (PMID 24722010, 2014). "Nevertheless, recent studies have observed haptoglobin expression associated with ovarian and breast tumors, as well as ovarian and embryonic lung cancer cell lines." (PMID 25484625, 2014). "HP polymorphism causes change in haemoglobin‐bind capacity, antioxidant and iron‐recycling activities, which may be important for effective oxidative stress response in lung cancer pathogenic process." (PMID 33528895, 2021). "In lung cancer diagnosis 16 putative biomarkers have been identified through research as effective means, three of which—haptoglobin, calprotectin, and zinc-a-2-glycoprotein—have been shown to have high sensitivity and great specificity." (PMID 41245374, 2025). "Overexpression of HP has been found in lung cancer, ovarian and breast cancers, as well as in glioblastoma and metastases." (PMID 38006431, 2023). "HP, a marker of red blood cell destruction and a main hemoglobin-binding protein, which increases in many inflammatory diseases, including lung cancer." (PMID 35174082, 2022). "Different authors found that circulating levels of HP increase with cancer stage and that HP is potentially useful in the clinical biomarker of lung cancer." (PMID 35174082, 2022). "Previous studies demonstrate that HP expressions are higher in the serum of patients with liver cancer, lung cancer, ovarian cancer, or other cancers than in the serum of healthy subjects." (PMID 35860021, 2022). "It was revealed that TXN2 up‐regulated and HP downregulated in lung cancer cell tissues of Xuanwei patients and 3 lung cancer cell lines." (PMID 33528895, 2021). "All these results suggested that TXN2 overexpression and HP depletion promoted lung cancer resistance were through attenuating ferroptosis." (PMID 33528895, 2021). "In vitro, both knocking down of TXN2 and overexpression of HP were observed to modulate sensitivity of lung cancer cell lines to erastin and RSL." (PMID 33528895, 2021). "We validated the changes of TXN2 and HP in proteomics using several lung cancer cell lines and clinic samples." (PMID 33528895, 2021). "Is has been demonstrated that plasma haptoglobin level increased in several solid tumors including breast cancer, colon cancer, pancreatic cancer, lung cancer and ovarian cancer where it is considered as an independent prognostic marker." (PMID 32620920, 2020). "In blood plasma, the increased amount of HP has been found in infection, inflammation, and various malignant diseases, including lung cancer." (PMID 31217907, 2019). "Through quantification using MS-based glycoproteomic approaches, Tsai and co-authors noticed that when compared to normal donors, the fucosylated haptoglobin (Hp) level increased significantly in serum of each subtype of lung cancer." (PMID 24872809, 2014). "Among APRPs, the Haptoglobin (Hp) β chain, serum amyloid A (SAA), and apolipoprotein A-1 (Apo A-1) proteins represent novel potential diagnostic markers for lung cancer." (PMID 22229091, 2011). "The protein produced by the HP gene has been shown to play an important role in lung cancer." (PMID 39872525, 2024). "Together, our results demonstrate that down‐regulated TXN2 and up‐regulated HP made the cancer cells more resistant, which could be a specific mechanism for the lung cancer in Xuanwei area." (PMID 33528895, 2021).
lung cancer (continued). "We hypothesized ‐ that regulating the levels of TXN2 and HP in lung cancer cells would influence the cell proneness to ferroptosis." (PMID 33528895, 2021). "We overexpressed TXN2 or interfered with HP in lung cancer cell lines (A549 and NCI‐H11299)." (PMID 33528895, 2021). "Moreover, we also observed that the ligand protein Haptoglobin (HP), which can be increased in lung cancer during infection and inflammation, is activated in middle stage LADC." (PMID 31217907, 2019). "Further experiments on the two differential proteins, thioredoxin 2 (TXN2) and haptoglobin (HP), showed that the change of their expressions could make the lung cancer cell lines more resistant to erastin or RSL‐induced ferroptosis in vitro, and promote the growth of tumour in nude mice." (PMID 33528895, 2021). "MCP1, HP and BAFF are linked to smoking in specific disease contexts and different tissues (e.g., bronchial secretions, and sgp130 has been linked indirectly to smoking via the STAT3 transcription factor pathway and modulation of tobacco carcinogen induced lung cancer." (PMID 34771561, 2021). "Salivary proteins with high specificity and sensitivity to identify lung cancer include calprotectin, AZGP1, and HP." (PMID 38202898, 2023). "Recently, using 2D-DIGE, we identified several proteoforms of blood plasma proteins from lung cancer patients, including proapolipoprotein, apolipoprotein AIV, clusterin, gelsolin, fibrinogen, haptoglobin, hemopexin, transferrin, and serotransferrin." (PMID 35512017, 2022). "TXN2 overexpression or HP depletion decreased erastin and RSL‐induced lipid oxidation in lung cancer cell lines, which were shown by the green fluorescence intensity (levels of oxidized C11 BODIPY 581/591)." (PMID 33528895, 2021). "Among which, SAA1, SAA2, HP, NAMPT, CHI3L1 and CHI3L2 have been reported to act as tumor promoters in multiple cancers including lung cancer, breast cancer and ovarian cancer." (PMID 38763993, 2024). "Specifically, in the present study, we supposed that HP and TXN2 may be involved in ferroptosis and contribute to lung cancer in Xuanwei area." (PMID 33528895, 2021). "In addition, some proteins such as haptoglobin hp2 (HP), zinc 2-glycoprotein (AZGP1) and calprotectin were differentially identified with high levels of sensitivity and specificity in the saliva of lung cancer patients." (PMID 32294884, 2020).